CXCL13 (C-X-C motif chemokine ligand 13)
Diseases named in the same sentence as CXCL13 in open-access papers (continued):
Sharing a sentence is not in itself a finding about the gene and the disease.
tumor (continued). "Moreover, in multiple myeloma, CXCL13 acts as a key mediator within the osteolytic niche, driving macrophage polarization toward an M2-like phenotype facilitating tumor progression." (PMID 41583429, 2025). "Key structural elements, including HEVs, organized T- and B-cell zones, FDCs/FRCs, homeostatic chemokines, and CXCL13-producing Tfh cells, foster GCs-like reactions, tumor-specific antibody production, and improve clinical outcomes when present in a mature form." (PMID 41374956, 2025). "In conclusion, this study, through single-cell RNA sequencing, reveals that the pre-existing proportion of CXCL13+ T cell subsets in tumor tissues is positively associated with non-recurrence following CCRT." (PMID 40464813, 2025). "Recent reports suggest that PD1, CD39, and CXCL13 mark tumor-reactive T cells." (PMID 40707674, 2025). "In addition, CXCL13 expression has been correlated with clonally reactive T lymphocytes that target tumor neoantigens." (PMID 40806532, 2025). "However, CXCL13 can induce B cells to produce the immunosuppressive cytokine IL‐10 in tumor tissues." (PMID 39344390, 2024). "Both in vivo and in vitro experiments demonstrated that PD1+CXCL13+CD8+T cell might represent a functional cell subtype exerting anti-tumor effects during the process of immune surveillance." (PMID 39493749, 2024). "These two effects mean that CXCL13 serves as a tumor-inhibiting gene." (PMID 39064019, 2024). "In addition, CXCL13+ cells can indirectly promote the growth of tumor cells by facilitating their evasion from immune responses mediated by effector T cells and by attracting immune cells that have an immunosuppressive function." (PMID 38398098, 2024). "Recent studies suggest that CXCL13+ T cells in the tumor microenvironment (TME) may be a good predictor of response." (PMID 38398098, 2024). "Meanwhile, ST analyses corroborated conspicuous aggregations of B lineage cells (Naïve B, Memory B, GC B, and plasma cells), CD4_C8_CXCR5 and CD8_C8_CXCL13 T cells, and CXCL13+ CAFs (iCAF_C2_CXCL13) in the TLS regions of NPC tumours across Stereo-seq and Visium cohorts." (PMID 39231979, 2024). "Similarly, in breast cancer, CXCL13 conjugated with CpG oligonucleotides to stimulate B cells and inhibit Breg cells has been found to reduce tumor metastasis." (PMID 39519376, 2024). "However, SFRP2, SPINK1, CXCL11, CXCL13, and CXCL10 exhibited gene copy loss in certain tumor populations." (PMID 38577604, 2024). "Furthermore, research by another team has demonstrated that T cell-mediated tumor reactivity manifests in brain metastases, characterized by the enrichment of CD39+ T cells expressing CXCL13, which are potential tumor-reactive T cells (pTRT)." (PMID 38396722, 2024). "Furthermore, the number of CXCL13+ T cells was positively correlated with pERK+ tumor cell ratio, revealing the role of CXCL13+ Tex cells in activating ERK signaling and shaping the prometastatic niche." (PMID 38519500, 2024). "Additionally, many chemokines or cytokines, such as CCL20, CXCL5, and CXCL13 (Cluster 9), had significantly different expression levels between the two populations, which indicates differences in the tumor microenvironment." (PMID 38166892, 2024). "Additionally, FDCs within TLS can secrete CXCL13 to attract B cells towards the tumor site, thereby promoting the formation and sustenance of TLS." (PMID 39026670, 2024). "Together, our study underscores a synergistic inflammatory immune response orchestrated by highly immunogenic tumor cells and CXCL13+CD4+ T cells in HPV+ OPSCC, offering useful insights into strategy development for patient stratification and effective immunotherapy in OPSCC." (PMID 39105803, 2024). "The results showed that the CXCL13 may also inhibit tumor progression and improve the prognosis of patients by inducing apoptosis of tumor cells." (PMID 38459390, 2024).
tumor (continued). "In the present study, we systematically profiled the cellular components of the TME in TNBC by scRNA-seq data, as well as identified signature genes of pro-inflammatory immune cells, including CXCL13+ tumor-reactive T cells, activated T cells, effector T cells, CXCL9+ TAMs, NK cells, and cDC1." (PMID 38533207, 2024). "Additionally, we demonstrate that during lymph node metastasis, exhausted CD8+ T cells with high CXCL13 expression strongly interact with tumor cells to acquire more aggressive phenotypes of extranodal expansion." (PMID 38519500, 2024). "Recent studies also report that CCR7+ DCs may engage other immune cells in tumours, including CXCL13+ CD4+ T cells, regulatory T cells and NK cells, and may reside in TLS12,15." (PMID 38267413, 2024). "Similarly, MMRd ECs are enriched in CD8+ T cells expressing high levels of PD-1, CD39, TIM-3 and CXCL13, which define a population of tumor-reactive T cells that was also positively correlated with the level of the TMB." (PMID 39544936, 2024). "The relatively low proportion of CD8_C8_CXCL13 T cells within NPC tumours (ranging from 0% to 11%) may potentially limit their anti-tumour activity." (PMID 39231979, 2024). "Furthermore, MMRd tumors contain abundant T cells with a strong CXCL13+ signature, suggesting effector tumor-specific T cells." (PMID 39544936, 2024). "Moreover, after activated by HPV+ tumor cells, CD4_C3_CXCL13 T cells were significantly enriched in HPV+ OPSCC and have been associated with a favorable prognosis, underscoring their potential as a prognostic biomarker." (PMID 39105803, 2024). "The TLS ratio, defined as the segmented TLS area over the total tissue area, correlated with B lymphocyte levels and the expression of CXCL13, a chemokine associated with TLS formation, in 6140 patients spanning 16 tumor types from The Cancer Genome Atlas (TCGA)." (PMID 38519580, 2024). "Interestingly, the distribution of CXCL13+T cells was particularly prominent in the obese tumor samples." (PMID 38311726, 2024). "In particular, we investigated whether CXCL13+ cell prediction performance was different in various compartments, including non-tumor (NT), invasive margin (IM), tumor (T), and TLS, even after accounting for other known predictive factors." (PMID 38398098, 2024). "In summary, our findings suggest that IFN-I signature enrichment is a distinguishing feature of tumor-infiltrating, tumor-reactive Ki67+ CXCL13+CD4+ T cells that license cDC1s for the induction of antitumor CTL activity in the TME, which potentially leads to a favorable clinical outcome." (PMID 38383773, 2024). "Furthermore, we observed that CD4+ CTLs produce CXCL13 that potentially interacts with activated B cell populations, including DN B cells, through physical conjugation in tumor lesions." (PMID 38077321, 2023). "In contrast CD28− TRM mainly produced CXCL13 within the tumor." (PMID 37898752, 2023). "And CXCL13 immunohistochemistry marker was related to the degree of tumor immune infiltration." (PMID 37219794, 2023). "We hypothesized that SC-2 CD4+ cells with high CXCL13 expression might also regulate anti-tumor immunity by assisting TLS formation." (PMID 36049666, 2023). "In addition, they demonstrated the curative effect of CXCL13 therapy in combination with ICB to enhance anti-tumor immunity in the KPAR orthotopic model." (PMID 38111571, 2023). "Furthermore, numbers of tumour reactive CXCL13+ CD8+ T cells were increased following anti-PD-1 treatment, indicating that expansion of this population is a hallmark of anti-cancer immunity." (PMID 37520560, 2023). "This suggests that the increased frequency of CXCL13+Texp in NSCLC post anti-PD-1 results from decreased pressure within the TME on newly infiltrating tumour reactive T cells to progress towards terminal differentiation upon stimulation, rather than phenotypic change in existing exhausted T cells." (PMID 37520560, 2023).
tumor (continued). "In addition, we conducted a Spearman correlation analysis to investigate the relationship between the expression levels of LAMP3, GZMB, and CXCL13 proteins and the cellular composition of the tumor microenvironment." (PMID 37512096, 2023). "We speculated that the differential expression of CXCL13 in different cell subsets may play distinct roles in tumor progression and immune promotion." (PMID 37675100, 2023). "The tumor size reduction by anti‐PD‐1 treatment was significantly diminished by CXCL13 depletion." (PMID 37097643, 2023). "TLSs are thought to promote the recruitment and activation of tumor antigen-specific T cells, while tumor-infiltrating T cells may also be the cause of TLS formation through CXCL13-mediated recruitment of immune cells." (PMID 37482608, 2023). "CXCL13 is also related to the process of epithelial mesenchymal transition (EMT) in tumor cells." (PMID 38155221, 2023). "In particular, CXCL13 is a core chemokine that recruits tumour-infiltrating B and T cells." (PMID 36890557, 2023). "Indeed, a meta-analysis across 7 tumor types indicated that CXCL13 expression was a strong predictor of ICB response." (PMID 37492581, 2023). "Among 28 chemokine genes available, CXCL9/10/11/CXCR3, CXCL13/CXCR5 and XCL1/XCR1 mRNA expression were significantly increased in RCC compared to normal kidney tissue and also strongly associated with tumor-infiltrating effector memory and central memory CD8+ T cells in all investigated collectives." (PMID 37006314, 2023). "Additionally, CXCL13+ TH1-like cells (T05) were also enriched in tumor sites, whereas CD4+ANXA1+ TCM (T02) and CX3CR1+ Teff cells (T04 and T09) were mainly detected in blood and ascites." (PMID 37488416, 2023). "Secondly, CXCL13 mRNA expression together with negative nodal status and small tumor diameter are the strongest independent factors associated with better RFS." (PMID 36765559, 2023). "Re-emerged clonotypes of pre-existing ISG-15+CD8+ T cells could be found after treatment, which gives rise to a CXCL13-expressing effector population in responsive EBV (+) tumours." (PMID 37735150, 2023). "Based on the strong evidence showing a correlation between CXCL13 and the formation of TLS,10, 14, 38 it is a reasonable assumption that high CXCL13 expression could influence the loco‐regional anti‐tumor immunity of tumors." (PMID 36453453, 2023). "Our analysis revealed similarities and differences in T cell biology between individuals, with the most pronounced differences observed in a subgroup of individuals with brain metastasis, characterized by accumulation of CXCL13-expressing CD39+ potentially tumor-reactive T (pTRT) cells." (PMID 37217652, 2023). "However, the function of the CCL19, CCL21/CCR7 and CXCL13/CXCR5 axes in tumor immunity is complicated." (PMID 37215990, 2023). "Most of these studies investigated the effects of CXCL13 secreted from CD68+CD206+ macrophages on tumor cells, however, whether the CXCL13 could regulate macrophages remains to be explored." (PMID 37936696, 2023). "Our results support that CXCL13 could be an important chemokine in shaping the immunoactive tumor microenvironment which affects the anti‐tumor effect of ICI." (PMID 36453453, 2023). "We depleted CXCL13 in a CT26 mouse tumor model to investigate whether CXCL13 contributes to tumor response to anti‐PD‐1 therapy." (PMID 37097643, 2023). "Importantly, combination of ARID1A and CXCL13 in baseline tumor tissues suggested improved overall survival compared to either single biomarker." (PMID 36980292, 2023). "We analyzed the expression and distribution of CXCL13 in the tumor microenvironment of CRC." (PMID 37675100, 2023). "Thus, our research provides an accurate and detailed reference to better understand the role of CXCL13 in tumor genesis, progression and prognosis, as well as the role of future immunotherapy." (PMID 35141160, 2022).
tumor (continued). "Importantly, elevated levels of CXCL13 both before and after tumor resection identified a subgroup of patients with significantly impaired outcomes following tumor resection." (PMID 36077611, 2022). "Future studies in mouse tumor models using selective knockout or neutralization of CXCL13 might help clarify the role of CXCL13 and potentially other chemokines in the antitumor response." (PMID 35439168, 2022). "However, in vivo growth of CXCL13-silenced MM cells was significantly suppressed, reflected by decreased tumor burden in the BM of mice injected with RPMI8226-CXCR4-GFP CRISPR-CXCL13 in comparison with the parental RPMI8226-CXCR4-GFP cells." (PMID 36217194, 2022). "Indeed, generally, CXCL13 has been shown to drive growth and invasive signals in many tumours, but also correlates with improved survival in other tumours, suggesting a context-dependent role for this cytokine in cancer progression." (PMID 35226704, 2022). "This means that CXCL13 inhibition can destroy tumor cells, and its combination therapy may improve patient outcomes." (PMID 35570844, 2022). "Further investigation revealed that tumor-infiltrating TFH cells produce CXCL13 to attract CXCR5+ CD8+ T cells and CXCR5+ B cells toward the germinal centers within the TLS, where both T cells and B cells are primed, reinforcing their cytotoxic capacity against cancer cells." (PMID 35053457, 2022). "In addition, there were cases in which immune cells in the tumor stroma also expressed high levels of CXCL13." (PMID 35552285, 2022). "Triple-positive CD8+ TILs could upregulate the expression of the cytokine CXCL13 to generate a tumor microenvironment adapted to coordinate antitumor B-cell responses." (PMID 36451828, 2022). "In contrast, plasma IL-6 level had no direct association with 4T1 tumour size, but correlated positively with factors that did, namely plasma G-CSF and CXCL13 levels." (PMID 35226704, 2022). "CCR5-CCL4/CCL5 and CXCR3-CXCL9/CXCL10/CXCL11/CXCL13 axis were significantly correlated with CD 4 T and CD 8 T cells, indicating that these chemokine–receptor pairs may recruit the T lymphocytes into tumor." (PMID 35530341, 2022). "Increased CXCL13 within the tumor microenvironment may further facilitate immunosuppression due to increased recruitment of CXCR5-expressing regulatory T (Treg) cells." (PMID 36217194, 2022). "We next hypothesized that the elevation in CXCL1, CXCL10 and CXCL13 in BTC patients might have a prognostic relevance following tumor resection." (PMID 36077611, 2022). "Therefore, our data provided a potential link between CXCL13 and tumor-supporting M2 macrophages in MM." (PMID 36217194, 2022). "CXCL13 may play an anti-tumor and prognostic protective role through T cell and NK cell mediated pathway and cytotoxicity." (PMID 35141160, 2022). "CXCL13 induction in MM BM milieu may further shape MM microenvironment composition in a paracrine way, recruiting various tumor-supporting immune cells." (PMID 36217194, 2022). "In conclusion, this study comprehensively revealed the expression profile for CXCL13 in human cancers, explored the correlation between CXCL13 expression levels and clinicopathological feature and prognosis, tumor cell biological characteristics, and tumor immunity." (PMID 35141160, 2022). "Thus, increased expression of CXCL13 in the tumor microenvironment attracts other subpopulations of immune cells with tumoricidal activity." (PMID 36555420, 2022). "From the IHC of initial surgical specimens with our original microarray data (KOV, GSE39204/55512, n = 28), the ratio of cases with TLS was significantly higher in those with high CXCL13 gene expression than in those with low CXCL13 gene expression in tumor specimens (P = 0.046)." (PMID 35552285, 2022). "It was reported that the overexpression of CXCL13 could promote the growth, migration, invasion, and epithelial-mesenchymal transformation of tumor cells." (PMID 35844446, 2022).
tumor (continued). "Interestingly, we noticed that the toxicity gene and CXCL13, which dictates effective responses to programmed death ligand 1 blockade genes, are upregulated during tumor cell evolution." (PMID 35634956, 2022). "From this, we could postulate and form a model that IL-6 acts to promote CXCL13 and G-CSF production, which may act independently to aid 4T1 growth, and that G-CSF also promotes neutrophil expansion that supports 4T1 tumour growth." (PMID 35226704, 2022). "B cells are recruited by CXCL13 to promote TLS formation in the tumor microenvironment." (PMID 35053457, 2022). "This fact argues against the hypothesis that circulating CXCL13 exclusively originated from BTC tumor cells, suggesting that they reflect a status of systemic inflammation that might originate from the BTC as well as the tumor microenvironment." (PMID 36077611, 2022). "CXCL13 may then act as a protumour factor and, with IL-6, promote B cell responses which also act on tumour growth." (PMID 35226704, 2022). "The performance of the CXCL13-based model in predicting the prognosis of low-risk and high-risk effect LUAD patients was verified, and the association between the model and the degree of tumor immune cell infiltration was investigated." (PMID 35844446, 2022). "Finally, the individual kinetics of CXCL13 before and after tumor resection were also indicative of patient outcomes." (PMID 36077611, 2022). "Here, we observed a positive correlation between postoperative CXCL13 levels and the leucocyte count (RS: 0.317, p = 0.025), suggesting that postoperative systemic inflammation was a potential driver of elevated CXCL13 levels after tumor resection." (PMID 36077611, 2022). "Interestingly, while the serum levels of CXCL1 and CXCL10 decreased postoperatively, we observed significantly increased values of CXCL13 after tumor removal." (PMID 36077611, 2022). "CXCL13 mediates B cell recruitment in tumor tissues while being essential for the formation of tertiary lymphoid structures (TLSs), and CXCL13+ CD103+ CD8+ TILs may play a critical role in mediating B cell recruitment and TLS formation in human tumors." (PMID 35844446, 2022). "Here, IL-6, promoted by the tumour microenvironment, may interact in concert with G-CSF to drive neutrophil protumour activity and also production of CXCL13." (PMID 35226704, 2022). "Plasma CXCL13 level also had a direct positive association with 4T1 tumour growth, but did not appear to correlate with plasma G-CSF level or myeloid cell counts." (PMID 35226704, 2022). "Therefore, a possible TIM-3 and CXCL13 co-expression pattern within the tumor infiltrating immune-repertoire was further evaluated by us." (PMID 36341460, 2022). "CCL21 was used in a syngeneic 4T1.2 mouse breast model to attract ILC3s to primary tumors, which then induces tumor stromal cells to secrete CXCL13, and then results in lymphotoxin and activates receptor of NF-κB ligands, which stimulate tumor cell migration and lymphangiogenesis." (PMID 36419156, 2022). "CXC chemokine ligand 13 (CXCL13) is an important factor involved in recruiting immune cells that express CXC chemokine receptor type 5 (CXCR5) in the tumor microenvironment and serves as a key molecular determinant of tertiary lymphoid structure (TLS) formation." (PMID 35053457, 2022). "CXCL13 may also serve as a prognostic and predictive factor, and the role played by CXCL13 in some ICI-responsive tumor types has gained intense interest." (PMID 35053457, 2022). "Accordingly, prevention of early B-cells recruitment in KrasG12D-PDEC orthotopically implanted mice with anti-CXCL13 treatment also resulted in reduced growth of the orthotopic lesions reinforcing possible tumor promoting properties of B-lymphocytes in the initial stages of PDAC development." (PMID 35359944, 2022).